SLC6A8 (solute carrier family 6 member 8)
Description:
Creatine:sodium symporter which mediates the uptake of creatine. Plays an important role in supplying creatine to the brain via the blood-brain barrier (By similarity).
Synonyms: CT1; CRTR; CRT; CRT-1; CRT1; CCDS1; CTR5
Tractability: Small molecule: it belongs to a druggable protein family. Antibody: UniProt places it where antibodies can reach, with high confidence; its Gene Ontology location is reachable by antibodies, with high confidence; UniProt predicts a signal peptide or a membrane-spanning region. PROTAC: ubiquitination databases record sites on it; a small molecule that binds it is known.
Target class: SLC superfamily of solute carriers; SLC06 neurotransmitter transporter family; Electrochemical transporter; Transporter
Gene: Protein-coding gene on chromosome X (153,687,926 to 153,696,591, forward strand). Ensembl gene ENSG00000130821.
Subcellular location: Cell membrane; Apical cell membrane
Pathways (Reactome):
Metabolism: Creatine metabolism
Gene Ontology:
Molecular function: creatine:sodium symporter activity; creatine transmembrane transporter activity; gamma-aminobutyric acid:sodium:chloride symporter activity
Biological process: creatine transmembrane transport; amino acid transport; creatine metabolic process; muscle contraction; sodium ion transmembrane transport; gamma-aminobutyric acid transport; neurotransmitter transport
Cellular component: apical plasma membrane; plasma membrane; membrane
Gene-disease validity (ClinGen):
ClinGen rates the evidence that SLC6A8 causes each of these diseases.
creatine transporter deficiency (X-linked): Definitive.
Homologues: Orthologues: chimpanzee SLC6A8 (100% identical), macaque SLC6A8 (99% identical), chimpanzee SLC6A8 (99% identical), mouse Slc6a8 (99% identical), rat Slc6a8 (98% identical), pig SLC6A8 (98% identical), guinea pig Slc6a8 (97% identical), dog SLC6A8 (95% identical), tropical clawed frog slc6a8 (75% identical), zebrafish slc6a8 (75% identical). Paralogues in human: SLC6A6 (53% identical), SLC6A13 (51% identical), SLC6A11 (51% identical), SLC6A12 (51% identical), SLC6A9 (41% identical), SLC6A5 (40% identical), SLC6A2 (40% identical), SLC6A7 (40% identical), SLC6A3 (40% identical), SLC6A14 (38% identical), SLC6A4 (38% identical), and 6 more.
Diseases named in the same sentence as SLC6A8 in open-access papers:
SLC6A8 is named in the same sentence as 118 diseases in open-access papers, as found by Europe PMC text mining. Sharing a sentence is not in itself a finding about the gene and the disease. The quoted sentences say what the papers report.
Creatine deficiency syndromes (20 papers, 2011 to 2025). "SLC6A8 deficiency, an X-linked disorder, causes cerebral creatine deficiency syndrome, which is associated with ID, epilepsy, and behavioral disorders." (PMID 39767570, 2024). "CTD (SLC6A8/CTD), an X-linked genetic disorder caused by a variant in the SLC6A8 gene located on the X chromosome, is one of three cerebral creatine deficiency syndromes (CCDS)." (PMID 40692578, 2025). "Indeed, mutations in SLC6A8 cause cerebral creatine deficiency syndrome (CCDS1: OMIM#300352)." (PMID 31906484, 2020). "For example, SLC6A8, which is linked to a creatine deficiency syndrome that causes mental retardation, severe speech delay, and seizures, and SLC7A7, which causes lysinuric protein intolerance are both missing in birds (OMIM), but have closely related paralogs that could provide compensation." (PMID 25518852, 2014). "Creatine deficiency syndromes (CDS), caused by mutations in GATM (AGAT), GAMT, and SLC6A8, mainly affect the central nervous system (CNS)." (PMID 38745894, 2024). "Creatine deficiency syndromes are characterised by intracerebral creatine deficiency due to deficiencies of creatine synthesis (deficiency of AGT or GAMT) and of the creatine transporter (SLC6A8 deficiency)." (PMID 25478001, 2014). "Creatine deficiency syndrome due to mutations in X-linked SLC6A8 gene results in nonspecific intellectual disability (ID)." (PMID 21910234, 2011).
Intellectual disability (19 papers, 2006 to 2026). "Creatine transporter deficiency (CTD) is an X-linked disorder due to the loss of SLC6A8 gene and presenting with low brain creatine, intellectual disability, autistic-like behaviour and seizures." (PMID 40729420, 2026). "Pathogenic variants in the creatine transporter gene SLC6A8, reported to represent 2% of all intellectual disabilities in males, result in a spectrum of behavioral abnormalities including developmental delay, intellectual disability, and deficit in speech." (PMID 40025148, 2025). "SV Cr was reduced in mice lacking either arginine:glycine amidinotransferase (a Cr synthetase) or SLC6A8, a Cr transporter with mutations among the most common causes of intellectual disability in men." (PMID 38126335, 2023). "Mutations in SLC6A8 were found in human patients with intellectual disability (ID), delayed language development, epileptic seizures, and autistic-like behaviors." (PMID 38126335, 2023). "Creatine (Cr) Transporter Deficiency (CTD) is an X-linked metabolic disorder, mostly caused by missense mutations in the SLC6A8 gene and presenting with intellectual disability, autistic behavior, and epilepsy." (PMID 34440297, 2021). "Another gene in the duplicated interval with developmental phenotypes is SLC6A8, a creatine transporter whose loss of function resulted in severe intellectual disability and autism." (PMID 22909152, 2012). "The girl diagnosed with SLC6A8 deficiency presented a severe phenotype similar to affected male patients, an observation that is not surprising in view of recent work also describing this X-linked disorder in the female population with intellectual disability." (PMID 23234264, 2012). "Creatine Transporter Deficiency (CTD), an X-linked disorder caused by mutations in the SLC6A8 gene, disrupts Cr transport, leading to intellectual disability, speech delay, autism, epilepsy, and various non-neurological symptoms." (PMID 39952955, 2025). "Pathogenic variants in SLC6A8, the gene which encodes creatine transporter SLC6A8, prevent creatine uptake in the brain and result in a variable degree of intellectual disability, behavioral disorders (e.g., autism spectrum disorder), epilepsy, and severe speech and language delay." (PMID 38632116, 2024). "This is particularly evident for mutants of the dopamine transporter (DAT/SLC6A3) and of the creatine transporter-1 (CrT1/SLC6A8), which are associated with a syndrome of infantile dystonia/Parkinsonism and intellectual disability/mental retardation, respectively." (PMID 29135937, 2017). "These authors characterized the presence of a mutation in the X-linked SLC6A8 gene in one patient with intellectual disability (ID) with absence of creatine in brain MRS and increased creatine in urine and plasma." (PMID 21910234, 2011). "Mutations in the solute carrier family 6-member 8 (Slc6a8) gene, encoding the protein responsible for cellular creatine (Cr) uptake, cause Creatine Transporter Deficiency (CTD), an X-linked neurometabolic disorder presenting with intellectual disability, autistic-like features, and epilepsy." (PMID 36882863, 2023).
epilepsy (16 papers, 2010 to 2025). A brain disorder characterized by episodes of abnormally increased neuronal discharge resulting in transient episodes of sensory or motor neurological dysfunction, or psychic dysfunction. "Dysfunctional extracellular matrix molecules in SLC6A8-deficient neurons are related to neurodegenerative disorders, learning and epilepsy." (PMID 30400883, 2018). "Intractable epilepsy in a female with heterozygous SLC6A8 mutation was completely treated by Cr." (PMID 38126335, 2023). "SLC6A8, an X-linked gene, encodes the creatine transporter (CRTR) and its mutations lead to cerebral creatine (Cr) deficiency which results in mental retardation, speech and language delay, autistic-like behaviour and epilepsy (CRTR-D, OMIM 300352)." (PMID 22713831, 2012). "Epilepsy has been reported as the second most common phenotype in GAMT deficiency and is also a frequent manifestation of SLC6A8 deficiency." (PMID 40323733, 2025). "CCDS1, caused by genetic variants in the SLC6A8 gene, is an X-linked inherited metabolic disorder with common clinical manifestations including mental retardation, severe speech disorders, epilepsy, movement disorders, and behavioral disorders." (PMID 40217354, 2024).
creatine transporter deficiency (13 papers, 2013 to 2026). X-linked creatine transporter deficiency (CRTR-D) is a creatine deficiency syndrome characterized clinically by global developmental delay/ intellectual disability (DD/ID) with prominent speech/language delay, autistic behavior and seizures. "BACKGROUND: Creatine Transporter Deficiency (CTD) is a rare X-linked disorder caused by pathogenic or likely pathogenic variants in the SLC6A8 gene, leading to a deficiency of cerebral Creatine." (PMID 41776642, 2026). "In a patient with cerebral creatine deficiency syndrome 1, due to a missense substitution in SLC6A8, supplementation with creatine was started." (PMID 39039281, 2024). "Creatine transporter deficiency (CTD) is an X-linked disease caused by mutations in the SLC6A8 gene." (PMID 37830910, 2023). "Variants, symptoms, biochemical assay results, and protein function from literature on the SLC6A8 gene associated with X-linked Creatine Transporter Deficiency (CTD) were curated and reported as a highly annotated dataset of variants with clinical context and functional details." (PMID 37587458, 2023). "Defects in SLC6A8 can result in X-linked creatine deficiency syndrome." (PMID 30400883, 2018). "Mutations in the creatine transporter gene SLC6A8, a member of the solute-carrier family 6 mapped to Xq28, have been reported to cause the creatine transporter deficiency." (PMID 30400883, 2018). "X-linked Creatine Transporter Deficiency (CTD) was chosen as an ideal candidate for manual curation because it is a monogenic disorder with a phenotype largely dependent upon the function of a single gene, SLC6A8, at a hemizygous location on the X chromosome." (PMID 37587458, 2023).
breast cancer (9 papers, 2010 to 2024). A primary or metastatic malignant neoplasm involving the breast. "Specifically, the expressions of Slc6a8 (solute carrier family 6 member 8), which encodes the creatine transporter was reported to be associated with breast cancer grade in TNBC patients." (PMID 36831625, 2023). "Expressions of Slc6a8, which encodes the creatine transporter protein, were detected in breast cancer cells and tissues by quantitative real-time PCR." (PMID 33990217, 2021). "Then, the upregulation of Slc6a8 was further confirmed in a set of different breast cancer cell lines that were cultured under normoxia or hypoxia for 24 h." (PMID 33990217, 2021). "A panel of six genes: CCNE2, DKFZp762E1312, EMP2, MAL2, PPIC, and SLC6A8 that were over-expressed in the blood of 81% of patients with recurrent breast cancer was then chosen as gene markers for the molecular detection of CTC." (PMID 21129172, 2010). "We have shown that the RT-qPCR-based multi-marker analysis using the six genes: CCNE2, DKFZp762E1312, EMP2, MAL2, PPIC, or SLC6A8 more than doubled the number of positive patients with recurrent breast cancer compared to the analysis of hMAM or EpCAM gene expression alone." (PMID 21129172, 2010). "The markers SCGB2A2, EpCAM, SLC6A8 and PPIC were detectable in about half of the metastatic breast cancer samples." (PMID 36831613, 2023). "In a recent study, using RT-qPCR, two panels of transcripts related to the presence of CTCs (Panel 1: CK19, EpCAM, SCGB2A2 and Panel 2: EMP2, SLC6A8, HJURP, MAL2, PPIC and CCNE2), in two cohorts of breast cancer patients (metastatic and early), were evaluated." (PMID 37046848, 2023). "In our present study, we evaluated two panels of transcripts related with the presence of circulating tumor cells (CTCs) (Panel 1: CK19, EpCAM, SCGB2A2 and Panel 2: EMP2, SLC6A8, HJURP, MAL2, PPIC and CCNE2) in two cohorts of breast cancer patients (metastatic and early)." (PMID 36831613, 2023). "Notably, upregulation of SLC6A8 was found to be inversely related to the overall survival in cancer of lung, breast and skin, relapse free survival (RFS) in cancer of the lung and breast, and distant metastasis-free survival (DMFS) in breast cancer." (PMID 36061183, 2022).
autism (5 papers, 2008 to 2025). Persistent deficits in social interaction and communication and interaction as well as a markedly restricted repertoire of activity and interest as well as repetitive patterns of behavior. "The existence of disruption in SLC6A8 paralogous gene associated with idiopathic autism suggests that this gene may be involved in the autistic phenotype in our patient." (PMID 18509488, 2008). "We sequenced GATM, GAMT and SLC6A8 genes in 166 patients with autism (coding sequence, introns and adjacent untranslated regions)." (PMID 28758966, 2017). "Coding and intronic regions have to be screened to establish ifmutations in the SLC6A8 paralogous gene are the cause of autism in a fractionof nontranslocation subjects." (PMID 18509488, 2008). "In summary, there were no apparent associations of variants in GAMT and SLC6A8 genes with autism." (PMID 28758966, 2017).
behavioral disorders (5 papers, 2021 to 2024). "Creatine deficiency may be manifested as intellectual and behavioral disorders, so we suspect that SLC6A8 is related to neurodevelopment in children with CHD." (PMID 39185136, 2024).
colon cancer (5 papers, 2015 to 2025). "SLC6A8 is also overexpressed in other cancer types, including gastrointestinal cancers where creatine metabolism has been implicated in colon cancer progression and metastatic colonization of the liver." (PMID 40903981, 2025). "A specific role of SLC6A8 in the “import” of metabolic energy in colon cancer cells has been also described." (PMID 26191006, 2015). "A recent report highlighted the role of SLC6A8 and creatine phosphate in the metastatic survival and colonization of colon cancer." (PMID 26191006, 2015). "SLC6A8 could modulate human creatine levels and suppress colon cancer progression." (PMID 39185136, 2024). "SLC1A4, SLC2A1, SLC3A2, SLC6A8, and SLC7A5 are transported as mRNAs by lung- and colon cancer-related exosomes." (PMID 41440381, 2025).
colorectal cancer (5 papers, 2018 to 2025). A primary or metastatic malignant neoplasm that affects the colon or rectum. "In tumors, previous study has demonstrated that SLC6A8 is overexpressed in human liver metastases compared with primary colorectal tumors and associated with enhanced colorectal cancer cell survival during hypoxic stress, suggesting the protective effects of SLC6A8 in cancer cells." (PMID 33990217, 2021). "An in vivo study has shown that inhibition of SLC6A8 inhibits colorectal cancer cell growth." (PMID 40867253, 2025). "On the other hand, blocking of SLC6A8 delayed cancer progression, and one inhibitor of this transporter (RGX-202) is tested in the treatment of advanced colorectal cancer in the first phase of clinical trials." (PMID 36835201, 2023). "SLC6A8 is called a creatine transporter, and RGX-202, a therapeutic agent that inhibits SLC6A8, inhibits the progression of colorectal cancer metastasis, indicating that creatine metabolism may be a therapeutic target." (PMID 40362545, 2025).
cognitive deficits (4 papers, 2014 to 2026). "Conditional mice with Slc6a8 deficiency restricted to this cellular population recapitulate the cognitive deficits, altered hemodynamic responses and abnormal susceptibility to KA observed in whole-body CrT−/y animals." (PMID 36882863, 2023). "Furthermore, significant cognitive impairments were observed in wild-type mice receiving gene therapy, highlighting a potential detrimental effect of ectopic expression of SLC6A8 in healthy brain circuits." (PMID 40729420, 2026). "The specific knockout of the creatine transporter gene Slc6a8 results in cognitive deficits." (PMID 39595102, 2024).
lung adenocarcinoma (3 papers, 2022). A carcinoma that arises from the lung and is characterized by the presence of malignant glandular epithelial cells. "However, there are currently no studies of SLC6A8 in lung adenocarcinoma (LUAD)." (PMID 35692837, 2022).
melanoma (3 papers, 2019 to 2022). A malignant, usually aggressive tumor composed of atypical, neoplastic melanocytes. "SLC6A8 was annotated to participate in melanoma (SLC6A10P‐SLC6A8) and glioblastomas (SLC6A8‐GABRA3) in FusionCancer." (PMID 30903738, 2019).
non-small cell lung carcinoma (3 papers, 2023 to 2025). A group of at least three distinct histological types of lung cancer, including non-small cell squamous cell carcinoma, adenocarcinoma, and large cell carcinoma. "Heat shock protein family D member 1 (HSPD1) promoted the progression of non-small cell lung cancer (NSCLC) dependent on SLC6A8 and COX5B." (PMID 41502520, 2025). "Non-small cell lung cancer lines H1299 with knockdown of SLC6A8 presented inhibited proliferation, whereas overexpression of SLC6A8 in H520 lines was connected with induced proliferation." (PMID 36835201, 2023). "In addition, overexpression of SLC6A8 promotes proliferation, migration, and invasion of non-small cell lung cancer, accompanied by upregulation of MMP9 and activation of the NOTCH 1 signaling pathway." (PMID 37234174, 2023). "During other studies, the bioinformatic analysis allowed to claim that in non-small cell lung cancer (NSCLC), the level of SLC6A8 was increased, and it was related to poor prognosis." (PMID 36835201, 2023).
X-linked disease (3 papers, 2020 to 2024). X-linked form of disease. "CT1 defect is a relatively common X-linked disease due to SLC6A8 mutation." (PMID 33363507, 2020).
lung carcinoma (2 papers, 2022 to 2025). "We specifically identified creatine metabolism as enriched in SqCC tumors, with associated elevated levels of the creatine transporter SLC6A8 gene in SqCC tumor cells, indicating specific metabolic fingerprints of lung cancer histologies." (PMID 40903981, 2025). "Altogether, SLC6A8 expression is elevated in lung cancer and its subtypes compared to normal tissues." (PMID 35692837, 2022). "Analysis from the Oncomine database revealed that SLC6A8 was highly expressed in a variety of cancers in which lung cancer is one of them." (PMID 35692837, 2022). "Moreover, the pattern of significantly higher SLC6A8 expression specifically in the SqCC histology compared to other lung cancer histological groups was observed also in our cohort of advanced‐stage lung cancers." (PMID 40903981, 2025). "To further investigate SLC6A8 and CHKA in lung cancer, we analyzed mRNA, protein, and metabolite expression of the two genes in lung cancer cell lines." (PMID 40903981, 2025). "To substantiate protein expression patterns of SLC6A8 in the discovery cohort, we investigated the expression of the gene using IHC in a TMA comprising 213 lung cancers (134 AC, 11 NE, and 68 SqCC tumors)." (PMID 40903981, 2025).